FLI1 (Fli-1 proto-oncogene, ETS transcription factor)
Diseases named in the same sentence as FLI1 in open-access papers (continued):
Sharing a sentence is not in itself a finding about the gene and the disease.
Ewing sarcoma (continued). "While the role of EWS/Fli1 as driver of aberrant cell proliferation, survival, oncogenic transformation and tumor growth is well established, much less is known about the mechanisms underpinning the high metastatic propensity of Ewing sarcoma." (PMID 33196691, 2020). "Our studies further identify a group of genes previously implicated in metastasis, whose opposing regulatory control by KDM5A/PHF2 and EWS/Fli1 may importantly contribute to modulation of Ewing sarcoma metastatic potency." (PMID 33196691, 2020). "However, the biology of the vast majority of epigenetic modifiers, and their phenotypic and mechanistic intersections with the EWS/Fli1 driver oncofusion, remain to be defined in Ewing sarcoma." (PMID 33196691, 2020). "Ewing sarcoma (EwS) is an aggressive cancer characterized by chromosomal translocations generating fusions of the EWSR1 gene with ETS transcription factors (in 85% FLI1)." (PMID 30741933, 2019). "Immunotherapeutic approaches including antigen-presenting cell-based vaccines have been employed as single agent or as part of combination strategies having been substantiated by a report on immunogenicity of Ewing's sarcoma with specific translocation resulting in EWS/FLI1 fusion." (PMID 31799177, 2019). "Together, these findings suggest that another mechanism by which JIB-04 could be acting in Ewing Sarcoma is exacerbation of EWS/Fli1 genotoxic effects." (PMID 30237855, 2018). "Although Ewing sarcoma is the most homogeneous entity among bone sarcomas, composed of undifferentiated round cancer cells characterised by CD99-, FLI1-, HNK1- and CAV1-positive immunostaining associated with limited stromal components, recent work demonstrated in contrast their heterogeneity." (PMID 29238848, 2018). "We were particularly intrigued by EWS/Fli1-repressed, anti-oncogenic miRs, as such miRs could conceivably be introduced into Ewing Sarcoma cells to inhibit cancer phenotypes." (PMID 28542597, 2017). "The EWSR1/FLI1 and EML4/ALK1 translocation common in solid tumors such as Ewing Sarcoma and lung cancer, could also generate associated f-circRNAs." (PMID 28279183, 2017). "As we previously observed for other EWS/Fli1-repressed miRs in our studies, miR-193b levels were lower in Ewing Sarcoma cell lines relative to hMSCs, further verifying miR-193b downregulation in Ewing Sarcoma." (PMID 28542597, 2017). "Fli-1 affects cellular proliferation and tumorigenesis in Ewing sarcoma and primitive neuroectodermal tumors., and additionally plays critical roles in normal development, hematopoiesis, and oncogenesis through its dual functions as a transcriptional activator and repressor." (PMID 28418872, 2017). "Ewing’s sarcoma (ES) is a highly aggressive and metastatic tumor in children and young adults caused by a chromosomal fusion between the Ewing sarcoma breakpoint region 1 (EWSR1) gene and the transcription factor FLI1 gene." (PMID 27740934, 2017). "The EWS/FLI1 fusion gene is a characteristic of Ewing’s sarcoma in most cases." (PMID 26969300, 2016). "In the form of EWS/FLI1 the transcription factor inhibits the expression of DKK1 in Ewing sarcomas but its role in SPN is still unknown." (PMID 27539223, 2016). "In Ewing sarcoma cell lines EWS/FLI1 suppresses expression of IGFBP3, but the transcriptional activity of the wildtype transcription factor FLI1 in SPN may differ." (PMID 27539223, 2016). "Indeed, FLI1 expression levels in Ewing sarcoma cell lines were highly correlated with olaparib sensitivity." (PMID 26095524, 2015). "The EWS/FLI1 fusion protein is an aberrant transcription factor that is essential for Ewing tumor development, since it regulates the expression of multiple target genes and governs the oncogenic processes that lead to malignant transformation of a yet undefined cancer precursor cell." (PMID 26258070, 2015). "It is well known that FLI1 drives Ewing sarcoma through a mechanism of EWS-FLI1 fusion oncoprotein." (PMID 26156017, 2015).
Ewing sarcoma (continued). "In addition, the expression of EWS/FLI1 in Ewing sarcoma was a significant marker of increased drug sensitivity (P-value = 0.0307, Mann-Whitney test)." (PMID 26337082, 2015). "The EWS-dependent regulation of SOX9 may also provide a platform for dissecting not only the role of EWS/FLI1 but also the development of Ewing sarcoma." (PMID 25617839, 2015). "Thus, EWS/FLI1 knockdown in Ewing sarcoma cells induces the expression of LOX indicating that this gene is strongly repressed by EWS/FLI1 in these cells." (PMID 26258070, 2015). "We present evidence suggesting that endogenous FLI-1-EWS is required for Ewing sarcoma growth and that FLI-1-EWS cooperates with EWS-FLI-1 in human mesenchymal stem cells, putative cells of origin of Ewing sarcoma, through abrogation of the proliferation arrest induced by EWS- FLI-1." (PMID 26807198, 2015). "To identify active promoter and enhancer elements in Ewing sarcoma and determine global binding of the oncogenic transcription factor EWS/FLI1, we performed chromatin immunoprecipitation coupled to high-throughput sequencing (ChIP-seq) in two Ewing sarcoma cell lines, TC32 and TC71." (PMID 26337082, 2015). "We have now discovered that FLI-1-EWS is frequently expressed in Ewing sarcoma and have obtained data indicating that endogenous FLI-1-EWS is required for Ewing sarcoma growth and that FLI-1-EWS cooperates with EWS-FLI-1 in human MSCs through abrogation of the growth arrest induced by EWS-FLI-1." (PMID 26807198, 2015). "Oncogenic activation of FLI1 leads to tumorigenesis, such as Ewing sarcoma and ovarian cancer." (PMID 26156017, 2015). "In addition, this pathway is rendered more oncogenic through increased EWS/FLI1-dependent expression of the cyclin D1B isoform in Ewing sarcoma." (PMID 26337082, 2015). "Thus, EWS/FLI1 knockdown in A673 and SK-PN-DW Ewing sarcoma cell lines downregulated CCK mRNA levels, demonstrating that CCK expression is dependent on EWS/FLI1." (PMID 26258070, 2015). "Finally, DAX-1 expression was demonstrated to depend on EWS/FLI1 expression in the A673 Ewing sarcoma cell line upon EWS/FLI1 knockdown." (PMID 26258070, 2015). "The expression of Fli-1 was predominantly found in the nuclei of Ewing sarcoma and leukemia." (PMID 24923303, 2014). "They then compared miR levels between control and EWS/Fli1-depleted cells, and between five Ewing Sarcoma patient tumors and mesenchymal stem cells (MSCs, the presumed cells of Ewing Sarcoma origin) from six different individuals, using a multiplexed RT-qPCR platform." (PMID 23543617, 2013). "Ewing sarcoma is characterized by chromosomal translocations that lead to the expression of chimeric transcription factors (the most frequent of which is the fusion protein EWS/FLI1), which are thought to be the responsible for tumor initiation." (PMID 23750284, 2013). "In addition, EWS/FLI1 has been also shown to regulate the expression of microRNAs that in turn are available to regulate the expression of other genes involved Ewing sarcoma tumorigenesis." (PMID 23750284, 2013). "Since EWS/FLI1 is the best established driver mutation in Ewing tumors, we sought to determine whether EWS/FLI1 can drive the expression of FOXM1." (PMID 23365673, 2013). "FLI-1, a marker for Ewing sarcoma, was present in 2 (5.5%) of 36 tumors." (PMID 24349741, 2013). "Interestingly, significant EWS/Fli-1 mRNA levels were detected in both fractions in all the Ewing sarcoma cell lines tested." (PMID 24124617, 2013). "Most Ewing sarcomas harbor gene fusions involving the FLI1, ERG, ETV1, ETV4, or FEV gene." (PMID 21789226, 2011). "Moreover, expression of this EWS/FLI-1 fusion protein in murine primary MSCs leads to the inhibition of MSC differentiation, and subsequent development of a EWS/FLI-1-dependent Ewing's sarcomas." (PMID 21437219, 2011). "Notably, human MSCs seem to represent a permissive environment for the expression of EWS/FLI1, which induces features in these cells that recapitulate Ewing's sarcoma biology." (PMID 21609503, 2011).
Ewing sarcoma (continued). "ES is a prevalent pediatric bone tumor characterized by the EWS (Ewing sarcoma breakpoint region 1)/FLI1 (friend leukemia integration 1 transcription factor) gene fusion." (PMID 41228282, 2025). "KDM6A and KDM6B mediate critical mechanisms behind EWSR1::FLI1 transcriptional activation program involving demethylase-independent and dependent functions, respectively, supporting the development of therapeutic strategies targeting these demethylases in Ewing sarcoma." (PMID 41085408, 2025). "The functional study showed that DAX1 is a physiologically significant target for EWS/FLI1-mediated oncogenesis, particularly Ewing Sarcoma (ES)." (PMID 37298283, 2023). "Genetically, Ewing sarcoma is driven by a fusion oncoprotein that results from one of a small number of chromosomal translocations composed of a FET gene and a gene encoding an ETS family transcription factor, with ~85% of tumors expressing the EWSR1::FLI1 fusion." (PMID 36672331, 2023). "Thus, EWSR1::FLI1 recruits and may be dependent on the complex, but perturbation the complex or its members may also be a sensitivity of Ewing sarcoma." (PMID 36793594, 2023). "Additionally, these investigators employed RNA interference to establish that GLI1 expression in Ewing sarcoma cells (specifically TC71) relies on EWS/FLI1, and it was confirmed that GLI1 expression plays a crucial role in maintaining the transformed phenotype." (PMID 37894854, 2023). "Cluster of differentiation 99 (CD99) and Friend leukemia integration 1 (FLI-1) are currently accepted for the diagnosis of Ewing Sarcoma but they can also be expressed in a wide range of cancer entities different from ES." (PMID 36776337, 2023). "The creation of humanized mouse models and an immune competent zebrafish model of Ewing sarcoma should enable new studies that can dissect the reciprocal interactions between EWS::FLI1 activity, tumor cell heterogeneity, and the immune TME and how they might impact on immunotherapy." (PMID 36505823, 2022). "Ewing sarcoma has been categorized as a ‘BRCAness’ tumor with emerging data characterizing a spectrum of DNA damage repair defects within individual Ewing tumors, including the presence of EWSR1::FLI1 itself, recurrent somatic mutations, and rare germline-based defects." (PMID 36483025, 2022). "Therefore, mitotic dysfunction induced by EWSR1/FLI1 may play a critical role in the induction of Ewing sarcoma." (PMID 33293370, 2021). "Ewing sarcoma (ES), the second most common bone cancer in adolescents and young adults (AYA), is caused by a pathognomonic genomic translocation that juxtaposes an N-terminal EWSR1 gene with one of several E26 transformation-specific (ETS) genes (typically FLI1 or ERG)." (PMID 32630797, 2020). "We thus asked whether JIB-04 treatment affects EWS/Fli1 levels in Ewing Sarcoma cells." (PMID 30237855, 2018). "This study may provide a platform for dissecting the EWS/FLI1 pathway in skeletal cells and to determine how skeletal differentiation is impaired in Ewing sarcoma cells in future studies, and it may provide insight into the formation of Ewing sarcoma." (PMID 25617839, 2015). "There are plenty of mechanisms regarding EWS/FLI1 target genes that are still unknown and a deeper knowledge on them could potentially lead to the development of more specific and less toxic therapies in Ewing sarcoma." (PMID 26258070, 2015). "We found a significant enrichment of our ChIP-seq-defined EWS/FLI1 target genes in the category of genes with high levels of H3K27Ac binding signal in their enhancer regions, consistent with enrichment of this oncogenic transcription factor at super-enhancers in Ewing sarcoma." (PMID 26337082, 2015). "Therefore diagnosis of Ewing sarcoma, pPNET or PNET (NOS), should be based on analysis of EWSR1 gene rearrangement or immunohistochemical analysis of FLI-1 not only on histological findings, associated with a limited immunophenotype usually represented by expression of CD99." (PMID 25960901, 2015).
Ewing sarcoma (continued). "The new models may help identify small molecule inhibitors that act directly on EWSR1::FLI1 fusion proteins or other genetic vulnerabilities within the altered epigenome and transcriptome, potentially contributing to a better understanding of Ewing sarcoma tumorigenesis." (PMID 41002248, 2026). "In this study, we integrate CUT&Tag with Global Run-On Sequencing (CUT, Tag, and GRO) to show that the minor groove binding compound, mithramycin (MMA), inhibits the Ewing sarcoma oncogenic driver, the EWS::FLI1 transcription factor." (PMID 41698909, 2026). "LSD1 and the pathognomonic fusion oncoprotein, EWSR1::FLI1, colocalize throughout the genome, suggesting that LSD1 is a critical co-regulator driving the progression of Ewing sarcoma." (PMID 41732136, 2026). "Here, the authors describe the establishment and characterization of four new, intrinsically immortal, patient‐derived Ewing sarcoma cell lines, including the first described cell line with an EWSR1::FLI1 type IV translocation." (PMID 41002248, 2026). "Ewing sarcoma is characterized by a fusion of the genes coding RNA-binding protein EWS and an ETS DNA-binding domain, most commonly EWS/FLI1." (PMID 41491919, 2026). "In Ewing sarcoma, chromosomal translocations lead to the formation of Ewing sarcoma breakpoint region 1- FLI1 (EWS-FLI1) fusion oncogene." (PMID 39816677, 2025). "The intersection obtained in A-673 was validated in a second Ewing sarcoma cell line, TC-71, in which we found 1,163 common peaks between EWSR1::FLI1 and KDM6A/KDM6B (P value < 0.05; FDR <10−5 in all cases)." (PMID 41085408, 2025). "In Ewing sarcoma, a CRC including KLF15, TCF4, and NKX2-2 MTFs that cooperate with EWSR1::FLI1 was reported in A-673 and EW-8 cells." (PMID 41444391, 2025). "Our findings demonstrated that Ewing sarcoma A673 cells, which harbor the EWS::FLI1 fusion, exhibit reduced cell viability upon POLE suppression." (PMID 40760094, 2025). "In ES (Ewing Sarcoma), hnRNPH1 regulates the splicing of the EWSR1::FLI1 fusion gene, promoting the production of oncogenic transcripts." (PMID 40507967, 2025). "The consistent high-level expression of CD99, coupled with an EWS gene rearrangement involving FLI1, ERG, or, in rare cases, other ETS genes, serves as hallmarks of Ewing sarcoma." (PMID 40427525, 2025). "In Ewing sarcoma (ES), cell surface markers such as CD99, Fli-1, and caveolin-1 are used in diagnostics, while glycosphingolipid ganglioside antigen G (D2) (GD2) can serve as a possible target for anti-GD2 monoclonal antibody therapy." (PMID 40134582, 2025). "KDM6A had a demethylase-independent role in recruiting BRG1 at EWSR1::FLI1-primed enhancers containing single GGAA motifs, which was critical for Ewing sarcoma tumor growth." (PMID 41085408, 2025). "To gain insight into the role of both demethylases on the EWSR1::FLI1 transactivation activity, we knocked down KDM6A and KDM6B in two Ewing sarcoma cell lines, A-673 and TC-71, using a doxycycline-inducible system." (PMID 41085408, 2025). "Ewing sarcoma (ES), characterized by the EWS::FLI1 fusion oncogene, is the second most common bone tumor in children." (PMID 40805174, 2025). "In Ewing sarcoma, a delicate balance between EWSR1::FLI1 and miR-145 has been reported as an essential oncogenic component." (PMID 40442778, 2025). "PC1 primarily separated MSC and EWSR1::FLI1-KD samples from the other entities, while PC2 segregated Ewing sarcoma samples." (PMID 41444391, 2025). "In Ewing sarcoma, small molecule YK-4-279 and its clinical derivative TK-216 have been labelled as first-in-class inhibitors of EWSR1::FLI1 and other EWSR1 fusions seen in Ewing sarcoma." (PMID 40983796, 2025). "According to all these data, it appears that over 90% of the chromoplectic rearrangements found in Ewing sarcomas are interchromosomal translocation involving the EWSR1 and FLI1 genes." (PMID 40332527, 2025).
Ewing sarcoma (continued). "Genetically, Ewing’s sarcoma is characterised by fusion of the EWSR1 genes, typically with the ETS gene, such as FLI1 in 90% or ERG in 5%; mergers with rarer partners are FEV, ETV1, and ETV4, but detection of these mergers alone is not diagnostic." (PMID 39941818, 2025). "CD99 positivity is seen in both MC and Ewing’s sarcoma, along with vimentin, CK, NKX2.2, FLI1, and CD99." (PMID 40585664, 2025). "The prototype of the characteristic histomorphology of small round cell sarcomas is the Ewing Sarcoma, which is exemplary defined by the chromosomal translocation of an FET gene family member with an ETS transcription factor, mostly EWSR1::FLI1." (PMID 40134582, 2025). "For example Ewing sarcoma, involving FET::ETS fusions (primarily EWSR1::FLI1), is predominantly a tumor of adolescents and young adults." (PMID 40852926, 2025). "In Ewing sarcoma, FET::ETS gene fusions, most commonly EWSR1::FLI1, are generated either by balanced chromosomal translocations or loop like rearrangements termed chromoplexy." (PMID 40442778, 2025). "The first research paper on this topic, published in 1994, focused on identifying Ewing’s sarcoma, osteosarcoma, and other small round cell sarcomas through the detection of EWS/FLI-1 (EWSR1) fusion transcripts." (PMID 41019082, 2025). "Ewing sarcoma arises from a chromosomal translocation event involving the EWSR1 and FLI1 genes, which can lead to the generation of the EWSR1-FLI1 fusion gene." (PMID 40584293, 2025). "Our prior results showed that treatment with the noncompetitive LSD1 inhibitor, SP-2509, reverses the transcriptional activity of both EWSR1::FLI1 and EWSR1::ERG in Ewing sarcoma." (PMID 40852926, 2025). "Next, we determined the sensitivity of PF1095 cells to the currently approved chemotherapies in comparison to two conventional Ewing sarcoma lines (EW-7 and MHH-ES1) with the two most frequent EWSR::FLI1 fusions." (PMID 40134582, 2025). "In Ewing sarcoma, for instance, inhibition of the EWS::FLI1 fusion protein can be achieved by blocking its epigenetic co-activators, P300 and CBP." (PMID 41228232, 2025). "Adamantinoma-like Ewing sarcoma (ALES) is a rare malignant neoplasm, identified as a type of Ewing sarcoma (ES), characterized by the EWSR1::FLI1 translocation and a complex immunoprofile." (PMID 40225424, 2025). "Our findings indicate a genome-wide gain of H3K27me3 in relevant genes from EWSR1::FLI1 pathways, supporting the important role of EZH2 in Ewing sarcoma tumorigenesis." (PMID 41085408, 2025). "Having shown that seclidemstat largely recapitulates the transcriptional effects of SP-2509, we also wanted to determine the degree to which seclidemstat disrupts EWSR1::FLI1 transcriptional activity and LSD1 function in Ewing sarcoma cells." (PMID 40852926, 2025). "In Ewing sarcoma cell lines, a direct interaction between the EWSR1::FLI1 fusion protein and PARP1 was described." (PMID 40134582, 2025). "We have recently demonstrated that genetic inactivation of EWSR1 : : FLI1 by CRISPR/Cas9, successfully blocks cell proliferation in a cell model of Ewing sarcoma." (PMID 40089636, 2025). "In Ewing sarcoma, the LCD of the EWSR1 protein fuses to the DNA-binding domain of an ETS transcription factor (e.g., FLI1), forming the EWSR1::FLI1 fusion oncoprotein." (PMID 41294805, 2025). "To test this possibility, we analyzed the genomic distribution of EWS::FLI1, cohesin, H3K27ac, p300, and CTCF using available ChIP-seq data from different Ewing sarcoma cell lines (Table EV1)." (PMID 39487368, 2024). "In summary, our findings demonstrate the EWS::FLI1/P300/CBP axis directly regulates the expression of key senescence-related genes LMNB1, promoting cell viability and preventing senescence in Ewing sarcoma and permissive cells." (PMID 39367409, 2024). "Many of these proteins, including EWS:FLI1 and EWS:ERG fusions in Ewing sarcoma (EwS) and TMPRSS2:ERG in prostate cancer (PCa), drive oncogenic programs via binding to GGAA repeats." (PMID 38530366, 2024).